DCAF4L2 (DDB1 and CUL4 associated factor 4 like 2)
Synonyms: WDR21C
Tractability: No criterion of Open Targets' tractability assessment is met for any kind of drug.
Gene: Protein-coding gene on chromosome 8 (87,870,747 to 87,874,015, reverse strand). Ensembl gene ENSG00000176566.
Gene Ontology:
Cellular component: Cul4-RING E3 ubiquitin ligase complex
Genetic constraint (gnomAD): Loss-of-function variants: 23 observed, 29.73 expected, observed/expected ratio (o/e) 0.77, 90% interval 0.56 to 1.1. The upper end of that interval is the gene's LOEUF score, 1.1, which puts it in group 4 of 6, group 1 being the genes least tolerant of losing a copy. Missense variants: 519 observed, 540.71 expected, observed/expected ratio (o/e) 0.96, 90% interval 0.89 to 1.03. Synonymous variants: 251 observed, 219.75 expected, observed/expected ratio (o/e) 1.14, 90% interval 1.03 to 1.27.
Homologues: Orthologues: macaque DCAF4L2 (96% identical), dog DCAF4 (75% identical), rat Dcaf4 (69% identical), mouse Dcaf4 (69% identical). Paralogues in human: DCAF4 (74% identical), DCAF4L1 (74% identical), AHI1 (14% identical), TEP1 (14% identical), WDR7 (14% identical), MAPKBP1 (13% identical), POC1A (13% identical), WDR75 (13% identical), POC1B (13% identical), SNRNP40 (13% identical), WDR5B (13% identical), WDR5 (12% identical), and 14 more.
Diseases named in the same sentence as DCAF4L2 in open-access papers:
DCAF4L2 is named in the same sentence as 12 diseases in open-access papers, as found by Europe PMC text mining. Sharing a sentence is not in itself a finding about the gene and the disease. The quoted sentences say what the papers report.
colorectal cancer (3 papers, 2020 to 2024). A primary or metastatic malignant neoplasm that affects the colon or rectum. "Studies have revealed that the levels of DCAF4L2 are higher in patients with lung cancer and colorectal cancer, which can lead to more advanced stages of the disease and the spread of cancer cells to other parts of the body." (PMID 38791918, 2024). "Wang et al56 found elevated DCAF4L2 expression in colorectal cancer was significantly correlated with clinical stage and it was an independent prognosis factor for survival." (PMID 32452127, 2020).
breast carcinoma (1 paper, 2012).
colonic cancers (1 paper, 2020). "Although overexpression of DCAF4L2 has been observed in human colonic cancers, its association with HCCs regardless of their etiology (viral hepatitis, heavy alcohol consumption or NASH) has never been reported." (PMID 32685988, 2020).
glioma (1 paper, 2020). A benign or malignant brain and spinal cord tumor that arises from glial cells (astrocytes, oligodendrocytes, ependymal cells). "Next, we evaluated the prognostic values of NPR1, DCAF4L2 and TSSK6 in human glioma patients by Kaplan–Meier analysis." (PMID 32452127, 2020). "We found that their homologous genes NPR1, DCAF4L2 and TSSK6 were highly expressed in glioma patients and patients with high NPR1 and TSSK6 predicted a short survival." (PMID 32452127, 2020). "Using the TCGA data sets, we found that NPR1, DCAF4L2 and TSSK6 were overexpressed in glioma samples compared with adjacent normal tissues in human." (PMID 32452127, 2020). "Notably, the expression of homolog gene DCAF4L2/F47D12.9, TSSK6/W02B12.12 and NPR1/gcy‐21 was found to be higher in glioma compared with adjacent normal tissue." (PMID 32452127, 2020).
hepatocellular carcinoma (1 paper, 2024). A malignant tumor that arises from hepatocytes. "DCAF4L2 has been shown to promote the progression of liver cancer, while EFNA3 and SPP1 have been treated as prognostic targets for survival in hepatocellular carcinoma patients." (PMID 39628446, 2024).
liver cancer (1 paper, 2024). An epithelial or non-epithelial malignant neoplasm that arises from the liver. "Particularly, several key genes, such as SLC27A5, IGF2, EFNA3, DCAF4L2, and SPP1, have been demonstrated to be associated with liver cancer." (PMID 39628446, 2024).
viral hepatitis (1 paper, 2020). An acute or chronic inflammation of the liver parenchyma caused by viruses. "Our data clearly revealed that overexpression of DCAF4L2 is a common feature of NASH-related HCCs and viral hepatitis-related HCCs." (PMID 32685988, 2020). "DNA hypomethylation of DCAF4L2, CKLF and UBE2C was observed in both NASH-related and viral hepatitis-related HCCs, whereas that of TRIM4, PRC1 and TUBA1B occurred in a NASH-related HCC-specific manner." (PMID 32685988, 2020).
cancer (5 papers, 2017 to 2025). A tumor composed of atypical neoplastic, often pleomorphic cells that invade other tissues. "DCAF4L2 was selected as the candidate gene due to its mutation being associated with shorter OS in the pan‐cancer cohort, esophageal/GC cohort, and only GC cohort." (PMID 39830022, 2025). "Introduction of DCAF4L2 in cancer cell lines has been shown to promote EMT, and this is considered attributable to activation of NF-ΚB signaling." (PMID 32685988, 2020). "The core CT genes include CMTM1, CT83 (CXorf61), EZHIP (CXorf67), DCAF4L2, KHDRBS3, LEMD1, PIWIL1, and SPATA6, which contribute to cancer progression and metastasis." (PMID 33426787, 2021).
tumor (5 papers, 2020 to 2025). "Patients with DCAF4L2 alteration in tumor tissue occupied a larger proportion of MSI‐type GC with a significantly higher average MSI MANTIS Score compared to those unaltered ones, which was in consistent with the pattern in our cohort." (PMID 39830022, 2025). "PD-L1 high-expressing tumors show hypermethylated genes and promoters with strong oncogenic effects (SNORD114-14, DCAF4L2, S100A7L2, and SOD1P3) and hypermethylated genes and promoters with tumor suppressor effects (CELF2-AS1 and LINCMD1)." (PMID 38791918, 2024). "There were 10 lncRNAs that were expressed in more than 20% of the tumor samples (LINC01980, AC025254.1, LINC02806, LINC02476, LINC02506, AL162413.1, LINC00221, LINC01287, AC079466.1, and LINC01419), compared to five protein-coding genes (MAGEA1, MAGEA3, SSX1, DCAF4L2, and MAGEC2)." (PMID 38985879, 2024).
DCAF4L2 also shares sentences with these, for which no sentence is quoted: lung carcinoma (2 papers); biliary tract cancer (1); leukemia (1).